TPD52 (tumor protein D52)
Diseases named in the same sentence as TPD52 in open-access papers (continued):
Sharing a sentence is not in itself a finding about the gene and the disease.
cancer (continued). "And TPD52 exhibited frequent overexpression in liver metastasis tissues relative to primary carcinoma tissues (P = 0.042), while MAL2 in lymphnode and liver metastasis tissues showed no significant elevation." (PMID 28562687, 2017). "Several studies showed that TPD52 was overexpressed in several cancers, and function as an oncogenes." (PMID 27765924, 2016). "TPD52 is overexpressed in several cancers, such as ovarian, breast, prostate, and pancreatic cancer, and multiple myeloma, Burkitt's lymphoma, and melanoma." (PMID 26575170, 2016). "Previous studies have indicated that TPD52 transcripts were dramatically downregulated in cancer patient blood cancer after radiotherapy." (PMID 27694690, 2016). "Genes such as TPD52, HOXB1, and KIF3A have been implicated in other cancer types and are connected with MCC-associated signaling." (PMID 24634783, 2014). "The TPD52 gene maps to chromosome 8q21.13, and demonstrates copy number increases and overexpression in a variety of cancers [reviewed in 31]." (PMID 20846453, 2010). "Tumor protein D52 (TPD52) is a small vesicle-trafficking protein that has been shown to be over expressed in a variety of human cancers." (PMID 21167051, 2010). "MAL2 and TPD52 staining were also compared in carcinomas according to histological subtype, and here differences between MAL2 and TPD52 expression emerged." (PMID 20846453, 2010). "Thus, our findings reveal de novo TPD52/ATF6‐mediated signaling activated during ER stress, which is abrogated by APCCdc20‐mediated polyubiquitination of TPD52 at K179, and thereby suggests synergistic strategies for cancer therapy." (PMID 39401430, 2024). "In addition, inactivation of Cdc20 sensitized cancer cells to treatment with the ER stress inducer in a TPD52‐dependent manner." (PMID 39401430, 2024). "TPD52 can be found to be overexpressed in several cancers and, to date, its function is largely unknown." (PMID 36142477, 2022). "Nevertheless, the role of TPD52 in the onset of cancer is still debatable." (PMID 35047407, 2021). "The tumor protein D52 (TPD52) family has important biological functions in several cancers." (PMID 34744715, 2021). "Additionally, upregulation of TPD52, involved in proliferation, migration, invasion and apoptosis, was found in many cancer types including AML65." (PMID 33712646, 2021). "The primary evidence of the importance of an altered expression of TPD52 in various cancers was obtained from the position of this gene on chromosome 8q, and during the mid-1990s, it became widely understood that the expression of TPD52 increases in certain tumor types, as well as in MYC oncogene." (PMID 35047407, 2021). "However, details regarding TPD52 in cancer cells under hypoxia are still to be investigated, and the following studies are now ongoing." (PMID 34217360, 2021). "However, the detailed roles of TPD52 in the proliferation and survival of cancer cells are still unclear." (PMID 34217360, 2021). "TPD52 expression is related to cell growth progression in various types of cancer cells." (PMID 34099820, 2021). "Through a literature review, it is also revealed that KLF3, TPD52, PKCε, and miR-124 interact with different downstream signaling molecules of these pathways in different cancers and lead to cancer proliferation, stage progression and metastasis, and drug resistance." (PMID 33490232, 2020). "Of these, TPD52 was the first to be identified nearly 20 years ago as an overexpressed gene in breast cancers; the gene is located on chromosome 8q21, a region frequently gained in various human cancers." (PMID 28798933, 2017). "Additionally, like MAL2, TPD52 mRNA level was detected by RT-qPCR and showed an increase in carcinoma tissues, indicating its overexpression due to gene amplification.MAL2 is a heterologous binding partner of TPD52." (PMID 28562687, 2017). "Currently, a collection of studies on the role of TPD52 in cancers is underway." (PMID 26575170, 2016).
cancer (continued). "Many of them such as Tumor protein D52, Prohibitin-2, Nucleophosmin, Elongation factor Tu(EF-Tu) have been previously reported as differentially expressed in PCa and closely related to oncogenesis and cancer progression." (PMID 21504578, 2011). "Interestingly, several of these small and large altered regions contain cancer-associated genes known to be involved in CRC and/or the metastatic process: i.e. the TPD52, FABP5, MAP2K4, LLGL1, FBLN1 and TYMP genes." (PMID 21060790, 2010). "Consequently, an elevated TPD52 protein abundance was detected in multiple cancer cell lines." (PMID 39401430, 2024). "Increased levels of TPD52 in SOL of brain may be a key player that leads toward cancer." (PMID 35577881, 2022). "However, inhibition of HIF with knockdown of TPD52 might induce cell death in cancer cells under hypoxia due to cellular starvation through aberrant acceleration of autophagy." (PMID 34217360, 2021). "This study showed that the expression of TPD52 increases in OSCC cells under hypoxia in a HIF-independent manner and plays an important role in the proliferation and survival of the cells in concordance with HIF, suggesting that novel cancer therapeutics might be led by TPD52 suppression." (PMID 34217360, 2021). "Therefore, the differential correlation of high TPD52 expression and OS of patients in several cancers may demonstrate different roles for TPD52 in cancer progression." (PMID 28562687, 2017). "A group of small proteins, known as the Tumor Protein D52 (TPD52)-like family, has been identified and is increasingly recognized for its roles in intracellular trafficking within cancer cells." (PMID 41677618, 2026). "Cdc20 catalyzes the polyubiquitination of TPD52 to mark it for degradation, leading to the downregulation of ATF6 and ER stress as well as the progression of cancers." (PMID 39401430, 2024). "We identified distinct genes including KLK4, FN1, PBOV1, TPM2, and FLNA which are known to be involved in PCa pathways along with IGF1, TPD52, and SRSF1 that are involved in different cancer pathways." (PMID 37218885, 2023). "Among the family members (TPD52, TPD53, TPD54, and TPD55), TPD52 has been extensively studied due to its involvement in the malignancy of different cancer cells." (PMID 37564195, 2023). "We verified the four up-regulated lncRNAs (TCONS_00020615, TCONS_00055555, TCONS_00106091, and TCONS_00130858) and eight cancer-related mRNAs (CDCA3, DIAPH3, MCM7, NCAPG2, TPD52, PRC1, SETD6, and KIF22) involved in the ceRNA network by qRT-PCR." (PMID 37098483, 2023). "However, the exact mechanisms of TPD52 in cancer metabolism remain unclear." (PMID 35666017, 2023). "The present study evaluated differential expression of four genes: PKCε, TPD52, KLF14 and miR-124 that are involved in modulation of Akt/PI3K and Ras/Raf/ERK1/2 signaling in different cancers." (PMID 35577881, 2022). "The expression of TPD52 and PKCε was lower in SOL patients in comparison to patients with high grade cancer (respectively)." (PMID 35577881, 2022). "Evaluation of gene expression levels for TPD52, miR-124, PKCε and KLF14 with respect to cancer grade was performed." (PMID 35577881, 2022). "The tumor protein D52 (TPD52) family reportedly plays an important role in the proliferation and metastasis of various cancer cells." (PMID 34744715, 2021). "TPD52 (CR542034.1) is situated at the 8q21 chromosome, on an area that is commonly amplified in numerous cancers particularly in humans." (PMID 35047407, 2021). "On the other hand, the other members (TPD52, TPD53, and TPD54) have been reported to be highly expressed in various cancers." (PMID 28798933, 2017). "This highlights the fact that TPD53 and TPD52 are positive regulators of Akt signaling in low-malignant cells, suggesting that TPD53 can enhance the proliferative and invasive potential of cancer cells by increasing MMP activity via the Akt pathway." (PMID 39767632, 2024).
cancer (continued). "Moreover, we found that TPD52, TF, and CCT6A were more frequently heterozygous amplified while STC2, CISD1, and P4HA2 were more likely to occur in heterozygous deletion in cancers." (PMID 36998462, 2023). "The expression of INV markers TPD52 and TPD54 is altered in different cancers, suggesting that the mechanism by which the INVs contribute to carcinogenesis may be via their role in integrin trafficking." (PMID 35657500, 2022). "It was observed that with an increase in proliferation and progression of cancer the expression of TPD52 protein increases, although there was no expression of TPD52 in RWPE (immortalized cells, nontumorigenic cells) and NB22 cells (least malignant)." (PMID 34099820, 2021). "It was observed that with the increase in proliferation and progression of cancer the expression of TPD52 protein increases, although there was no expression of TPD52 in RWPE (immortalized cells, nontumorigenic cells) and NB22 cells (least malignant)." (PMID 34099820, 2021). "Furthermore, we focused on the seven lncRNAs (PFKL, TPD52, ERGIC3, CFL1, CARS, IARS, and H19), which were related to cancer development." (PMID 32485786, 2020). "Tumor protein D52 (TPD52) is an oncogene amplified and overexpressed in various cancers." (PMID 31649118, 2019). "Immunohistochemical analyses showed that MAL2 (P<0.001) and TPD52 (P<0.001) were significantly highly expressed in primary carcinoma tissues compared with adjacent non-cancerous mucosa tissues." (PMID 28562687, 2017). "Although TPD52 has been investigated in several cancers, to our knowledge, there are no reports on its expression and prognostic value in HCC." (PMID 26575170, 2016). "Whereas the cancer epithelial cell-enriched proteins were characterized of proliferation feature, such as hepatoma-derived growth factor (HDGF), bone morphogenetic protein 7 (BMP7) and tumor protein D52." (PMID 26338966, 2015). "Additionally, although the individual expression status of TPD52, KLF9, miR-223, and PKCε has been previously studied in various tumors, no study has investigated the co-expressions of TPD52, KLF9, miR-223, and PKCε in any cancer type." (PMID 35047407, 2021). "Of them, thymidine phosphorylase, E3 ubiquitin-protein ligase, and tumor protein D52 are involved in processes of angiogenesis, tumor growth, or metastasis and the rest are proteins with different physiological functions and no reported involvement in cancer development or progression." (PMID 25215235, 2014). "However, MAL2 (n = 58, P = 0.55) and TPD52 (n = 58, P = 0.672) protein expressions in lymphnode metastasis tissues (data not shown) and MAL2 expression in liver metastasis tissues (n = 38, P = 0.782) did not exhibit significant elevation relative to primary carcinoma groups." (PMID 28562687, 2017).
tumor (59 papers, 2008 to 2025). "Our findings reveal that TPD52 is associated with immune regulation and has significant implications for tumour behaviour and patient prognosis." (PMID 39757112, 2025). "Intraperitoneal injection of MEM considerably slowed tumor growth in athymic mice, inhibited TPD52 expression, and caused a marked reduction in PSA levels of serum as demonstrated by immunoblot screening and immune-histochemical staining." (PMID 34099820, 2021). "This suggests that the lower expression of KLF3 and miR-124 and enhanced expression of TPD52 have association with tumor metastatic potential and stage progression." (PMID 33490232, 2020). "We firstly identified two signal transduction-associated proteins (syntenin and Ras small GTPase) and one tumor-associated protein (tumor protein D52) from the purified NDV particles." (PMID 22571704, 2012). "The association of TPD52 with specific mutation sites and high mutation rates may indicate its role in driving tumour evolution and heterogeneity." (PMID 39757112, 2025). "In addition, loss of TPD52 promoted behaviors associated with tumor progression in vitro and in vivo." (PMID 39401430, 2024). "Therefore, TPD52 is a novel, potentially important tumour-associated antigen that is highly expressed in a variety of tumour cells, affecting their biological function by regulating their proliferation, apoptosis, invasion, and migration." (PMID 34565443, 2021). "Further correlation analysis exposed that the reduced expression of TPD52 in HCC was suggestively linked to advanced stage tumor, signifying that a reduced TPD52 expression may promote tumor metastasis." (PMID 35047407, 2021). "MAL2 and TPD52 staining in tumor cells and associations with clinicopathologic characteristics." (PMID 28562687, 2017). "Paradoxically, in malignant insulinomas, TPD52 downregulation correlates with aggressive phenotypes and poor survival, serving as a tumor suppressor and a prognostic stratifier." (PMID 40973691, 2025). "TPD52 was identified as a tumor-promoting gene, and its knockdown suppressed TNBC cell proliferation and migration." (PMID 40365116, 2025). "In the present investigation, TPD52 exhibited tumor-specific overexpression in GC tissues, and its expression levels positively correlated with patient age and the lymph node metastasis burden." (PMID 40973691, 2025). "Then, the “genes” module analysis showed that TPD52 expression was correlated with tumor purity and B cells, and it is markedly positively correlated with infiltration levels of CD8 + T cells in PRAD." (PMID 40341647, 2025). "Collectively, these results support the idea that TPD52 knockdown contributes to resistance to ER stress‐mediated inhibition of tumor progression both in vitro and in vivo." (PMID 39401430, 2024). "Our findings demonstrate that PKC functions in the AKT pathway since it is positioned upstream of TPD52 and can activate the route, perhaps increasing Tumor development and dissemination." (PMID 37833790, 2023). "PKCε is located upstream of TPD52 and both genes activate Akt signaling that promotes tumor proliferation and invasion." (PMID 35577881, 2022). "An elevated TPD52 expression was found to be increasing colony formation, cell proliferation, and tumor migration/invasion." (PMID 35087592, 2022). "Taken together, these results indicate that knockdown of TPD52 reduced tumor cell viability at the hypoxic center of the tumor, and that PX-478 showed similar effects." (PMID 34217360, 2021). "TPD52 knockdown with the addition of PX-478 in tumor-xenograft mice demonstrated decreased tumor volume, as observed in the in vitro study." (PMID 34217360, 2021). "Results of TPD52 staining showed that there is a decrease in expression of these proteins in MEM treated CWR22Rν1 athymic nude mice tumor xenografts resulted in inhibition of proliferation as represented by a decrease in tumor volume by MEM treated groups." (PMID 34099820, 2021).
tumor (continued). "In immunohistochemistry, knockdown of TPD52 and addition of PX-478 each induced cell death at the center of the tumor, where the environment was most hypoxic." (PMID 34217360, 2021). "We found that PKCε is located upstream of TPD52, and both of these genes activate the Akt pathway, which promotes tumor proliferation and invasion." (PMID 35047407, 2021). "Similar to in vitro data, intraperitoneal injection of MEM considerably slowed tumor growth in athymic mice, inhibited TPD52 expression, and resulted in a considerable reduction in the level of PSA in the serum." (PMID 34099820, 2021). "In this study, we explored the expressions of MAL2 and TPD52 in tumor specimens resected from 123 CRC patients and the prognostic values of the two proteins in CRC." (PMID 28562687, 2017). "Decreased p21 expression was also seen in most tumor tissues (P = 0.0024), and low expression of p21was found in the samples which low express TPD52." (PMID 26575170, 2016). "The correlation analysis suggested that TPD52 expression was significantly correlated with tumor-nodes- metastasis (TNM) stage (P = 0.011)." (PMID 26575170, 2016). "Consistent with the real-time quantitative PCR results, TPD52 protein expression was decreased in 17/25 (68%) tumor tissues (P = 0.039)." (PMID 26575170, 2016). "The neoplasm metastasis associated genes KRT20, tumor protein D52 (TPD52), MUC1, and KIT are upregulated in the poor prognosis tumors while homeobox B1 (HOXB1) is downregulated." (PMID 24634783, 2014). "From the results of the microarray analysis, we selected 5 genes i.e., K-ras, c-MYC, DNMT1, Tpd52, CDKN1b for PCR confirmation because they are already considered as tumor-related genes." (PMID 22206623, 2011). "Furthermore, immune infiltration analysis revealed the impact of the LINC01122/TPD52 axis on the tumor immune microenvironment and the progression of PCa." (PMID 40341647, 2025). "Our findings indicate that TPD52 may modulate immune cell infiltration and the tumour immune landscape, impacting tumour aggression and patient survival." (PMID 39757112, 2025). "Future research should focus on elucidating the precise mechanisms through which TPD52 influences immune responses and tumour behaviour, which could pave the way for innovative therapeutic strategies in BRCA management." (PMID 39757112, 2025). "Preliminary findings suggest that TPD52 may influence immune cell infiltration and modulate the tumour immune landscape, thereby impacting tumour aggression and patient survival." (PMID 39757112, 2025). "Together, these results suggested that the differences induced by the LINC01122/TPD52 axis might have an effect on the modifications of the tumor immune microenvironment and the development of PRAD." (PMID 40341647, 2025). "Moreover, miR-139-5p was expressed at higher level in normal tissues as compared to tumor tissues, while TPD52 expression exhibited the opposite pattern, with higher expression in tumor tissues." (PMID 37564195, 2023). "Abnormal sphingolipid metabolism and fatty acid oxidation in AML indicated that TPD52 may be a potential tumor marker with prognostic value in AML." (PMID 36193167, 2022). "In addition, overexpression of TPD52 was reported to increase tumor growth, demonstrating its physiological and pathological role." (PMID 34217360, 2021). "Notably, knockdown of TPD52 in addition to inhibition of HIF drastically decreased tumor volume, indicating a strong synergistic effect." (PMID 34217360, 2021). "TPD52 (Murine) causes the progression of NIH3T3 fibroblasts and tumor formation." (PMID 34099820, 2021). "Similarly, a histological specimen of a tongue OSCC tissue shows the expression of TPD52 at a hypoxic region in the tumor." (PMID 34217360, 2021). "In the light of this evidence, we observed different cellular localization of OAT, LTC4S and TPD52 in PCa cells procured from AA and CA, which may imply a possible role in tumor aggressiveness in AA but it needs further studies." (PMID 30397274, 2018).